MAP2K7 (mitogen-activated protein kinase kinase 7)
Diseases named in the same sentence as MAP2K7 in open-access papers (continued):
Sharing a sentence is not in itself a finding about the gene and the disease.
schizophrenia (8 papers, 2017 to 2024). A major psychotic disorder characterized by abnormalities in the perception or expression of reality. "The genetic association between MAP2K7 and schizophrenia correlated with impaired working memory in Map2k7 heterozygous mice." (PMID 39717752, 2024). "Because haploinsufficiency and conditional MAP2K7 gene deletion were associated with lymphocyte hyperproliferation, schizophrenia, neuropathy, and depression, systemic MAP2K7 inhibition may cause side effects due to off-tissue activity." (PMID 39717752, 2024). "We speculate that there is a possibility that this reflects the association of sequence variations in the MAP2K7 gene with risk for panic disorder as well as schizophrenia." (PMID 35275161, 2022). "The impact of MAP2K7 haploinsufficiency on behavioral tasks was studied because post-mortem brain analysis showed lower MAP2K7 expression in individuals with schizophrenia compared to brain tissue from healthy individuals." (PMID 39717752, 2024). "In fact, Map2k7+/− mice behaved in a very similar way to that seen in patients with schizophrenia in the IGT study, in which task contingencies were also altered." (PMID 35275161, 2022). "Accumulating evidence implicates a role for MAP kinase kinase 7 (MAP2K7), a JNK activator encoded by the Map2k7 gene, and other JNK pathway components in schizophrenia (ScZ)." (PMID 31219577, 2020). "Mutations in JNK3 cause severe intellectual disability, whilst sequence variations in the MAP2K7 gene (encoding MKK7) are associated with prefrontal cortex dysfunction and cognitive impairment in schizophrenia." (PMID 27774567, 2017). "The influence of Map2k7 on cytokine/chemokine induction converges the genetic and environmental aspects of schizophrenia, and the overt influence of maternal genotype offers an intriguing new insight into modulation of embryonic neurodevelopment by genetic risk." (PMID 30691477, 2019). "Interestingly, a potential indirect role for c-Jun in a preclinical model of schizophrenia pathophysiology has been recently highlighted by investigating attentive function in mice haploinsufficient for Map2k7 (Map2k7+/− mice)." (PMID 29321734, 2017). "Knocking out MAP2K7 results in schizophrenia-like behavioral deficits in mice." (PMID 29066733, 2017). "Mice hemizygous for a functional deletion of the Map2k7 gene (Map2k7 Hz mice) show reduced CNS expression of MKK7, along with subtle cognitive deficits characteristic of patients with schizophrenia, including an inability to sustain attention in cognitive tasks." (PMID 30691477, 2019).
depression (7 papers, 2017 to 2024). "Another group reported that loss of MAP2K7, using the same conditional gene deletion approach, did not alter locomotor functions and cognitive capacity; however, the mice presented social depression-like behavior." (PMID 39717752, 2024).
cognitive deficits (6 papers, 2017 to 2023). "Overall, Map2k7 haploinsufficiency causes a distinctive pattern of cognitive impairment strongly suggestive of an inability to sustain attention, in accordance with those seen in psychiatric patients carrying out similar tasks." (PMID 27774567, 2017). "Here, we test the hypothesis that reduced MKK7 expression is sufficient to cause cognitive impairment by investigating attentional function in mice haploinsufficient for Map2k7 (Map2k7+/− mice) by using the 5-CSRTT." (PMID 27774567, 2017). "The reduction of Map2k7 function has been found to be associated to cognitive deficits in mice." (PMID 29321734, 2017). "Deficits in prefrontal cortex-dependent working memory and cognitive impairments were observed in MAP2K7+/− mice mainly seen as impaired attention, a vigilance decrement deficit and unstable cognitive processing in an attentional task." (PMID 37779136, 2023). "Mice haploinsufficient for Map2k7 (Map2k7+/− mice) display ScZ-relevant cognitive deficits, although the mechanisms are unclear." (PMID 31219577, 2020). "In summary, mice haploinsufficient for the Map2k7 gene show deficits in attention, a core cognitive impairment in many neuropsychiatric diseases, and show signs of improvement in attentional performance with minocycline treatment." (PMID 27774567, 2017).
liver cancer (6 papers, 2015 to 2025). An epithelial or non-epithelial malignant neoplasm that arises from the liver. "Our study showed that MAP2K7, as a predictive marker, can well predict the occurrence of liver cancer, and as a prognostic marker, it can reflect the OS and RFS of female patients." (PMID 40587753, 2025).
diabetes (5 papers, 2012 to 2024). "In line with previous reports, the results of our functional enrichment analysis of PTEN, PRKCA, CALR, MAP2K7 argue for their involvement mainly in the regulation of the oxidative stress response in diabetes." (PMID 39080630, 2024).
heart failure (5 papers, 2007 to 2024). Inability of the heart to pump blood at an adequate rate to meet tissue metabolic requirements. "Conditional deletion of the Map2k7 gene in Map2k7fl/fl myosin-cre revealed that MAP2K7 promotes cardiomyocyte survival, suppressing extracellular matrix deposition and inhibiting hypertrophic growth, and thus preventing heart failure in response to pressure overload." (PMID 39717752, 2024).
T-cell acute lymphoblastic leukemia (5 papers, 2011 to 2025). Acute lymphoblastic leukemia of T-cell origin. "Our group discovered that the MAP2K7-JNK pathway is aberrantly activated in children with T-cell acute lymphoblastic leukemia (T-ALL)." (PMID 39717752, 2024). "Among the nine small molecules with MAP2K7 inhibitory capacity described in the literature, only four were evaluated in cancer models, predominantly multiple melanoma and T-cell acute lymphoblastic leukemia, and three were assessed in mouse models." (PMID 39717752, 2024). "Additionally, some studies have shown that KLF4 inhibits MAP2K7, and its deletion can activate MAP2K7 in T-cell acute lymphoblastic leukemia (ALL)." (PMID 40406144, 2025).
triple-negative breast carcinoma (5 papers, 2016 to 2025). An invasive breast carcinoma which is negative for expression of estrogen receptor (ER), progesterone receptor (PR), and human epidermal growth factor receptor 2 (HER2). "Map2k7 was shown to be upregulated in triple-negative breast cancer (TNBC) and negatively correlated with the level of miR-125b." (PMID 33921710, 2021). "MAP2K7 is a therapeutic target for triple-negative breast cancer." (PMID 40587753, 2025).
colorectal tumor (4 papers, 2006 to 2025). "A significant association was found between MAP2K7 and MAPK9 expression and the histological grade of colorectal tumors." (PMID 41515982, 2025).
acute lymphoblastic leukemia (3 papers, 2021 to 2025). Leukemia with an acute onset, characterized by the presence of lymphoblasts in the bone marrow and the peripheral blood. "Supporting a suppressive role in leukemia, KLF4 inhibits T-cell acute lymphoblastic leukemia (T-ALL) and KLF4 expression is silenced in pediatric T-ALL by CpG promoter methylation, which was associated with aberrant expression of MAP2K7, a kinase pathway that accelerates disease progression." (PMID 33659038, 2021).
Anxiety (3 papers, 2015 to 2025). Intense feelings of nervousness, tension, or panic often arise in response to interpersonal stresses. "We hypothesise that the Map2k7 hemizygous mice are showing a form of harm avoidance behaviour, and that full function of the Map2k7 gene is necessary for overcoming this anxiety-related contribution to cognitive flexibility." (PMID 39931698, 2025).
COVID-19 (3 papers, 2022). A disease caused by infection with severe acute respiratory syndrome coronavirus 2. "Mitogen-activated Protein Kinase 7 (MAP2K7) encodes for an augmenter of the c-Jun kinase pathway during T-cell activation and is elevated in severe COVID-19." (PMID 36143338, 2022).
pancreatitis (3 papers, 2017 to 2024). Inflammation of the pancreas. "In a model of inflammatory ductal metaplasia, mice with the dual loss of MAP2K4 and MAP2K7 could not efficiently resolve pancreatitis, leading to only partial acinar regeneration." (PMID 39717752, 2024).
endothelial dysfunction (2 papers, 2020 to 2024). In vascular diseases, endothelial dysfunction is a systemic pathological state of the endothelium (the inner lining of blood vessels) and can be broadly defined as an imbalance between vasodilating and vasoconstricting substances produced by (or acting on) the endothelium. "Similarly, CALR, encoding calreticulin, an endoplasmic reticulum stress marker, and MAP kinase kinase 7 (MAP2K7), a key upstream transducer of stress-activated protein kinase, have been evidenced as vital contributors to endothelial dysfunction in an oxidative stress environment." (PMID 39080630, 2024).
lymph node metastases (2 papers, 2022 to 2025). "Higher levels of MAPK8 and MAP2K7 gene expression were observed in patients with lymph node metastases (number 1–3) compared to patients without lymph node involvement (p = 0.0382; p = 0.0079)." (PMID 41515982, 2025).
astrocytic tumor (1 paper, 2025). A glial tumor of the brain or spinal cord showing astrocytic differentiation. "To investigate potential epigenetic regulation of inflammatory mediators, we analyzed the promoter methylation status of TNF-α, IL-1β, MAP3K8, and MAP2K7 in astrocytic tumors across different malignancy grades." (PMID 40565357, 2025).
chronic hepatitis (1 paper, 2018). An active inflammatory process affecting the liver for more than six months. "MAP2K7 and MAPK14 were highly expressed in chronic hepatitis; LAT, SOS2, and BCL‐10 were highly expressed in normal tissues; PTPN6, LCK, and CTLA4 were highly expressed in CS." (PMID 30259695, 2018).
Huntington disease (1 paper, 2016). Huntington disease (HD) is a rare neurodegenerative disorder of the central nervous system characterized by unwanted choreatic movements, behavioral and psychiatric disturbances and dementia. "It was interesting to note that genes involved in Huntington’s disease were enriched in this signature, namely MAP2K7, PDPK1, NCOR2, EP300, and REST." (PMID 27698411, 2016).
ischemic stroke (1 paper, 2021). A stroke disorder caused by obstruction of blood flow to the brain, due to thrombotic (local blood clot formation) or embolic (due to a blood clot or other material traveling from another site) event. "In addition to MAP2K7, 5Z7O has been investigated as a TAK1 inhibitor in multiple disorders such as ischemic strokes, inflammatory diseases, and cancer." (PMID 34504651, 2021).
prostatic intraepithelial neoplasia (1 paper, 2024). "Increased levels of MAP2K4, MAP2K6, and MAP2K7 in mouse prostate TRAMP model and tissues from patients with high-grade prostatic intraepithelial neoplasia." (PMID 39717752, 2024).
psoriasis (1 paper, 2024). An autoimmune condition characterized by red, well-delineated plaques with silvery scales that are usually on the extensor surfaces and scalp. "We demonstrated a potential relationship between DUSP1 and miR-34a; DUSP4 and miR-34a, miR-382, and miR-3188; MAPK9 and miR-1275, MAP2K7 and mir-200-5p; MAP3K2 and mir-200-5p, which may be the subject of further research in the context of psoriasis." (PMID 38445655, 2024). "Nevertheless, we demonstrated a potential relationship between DUSP1 and miR-34a; DUSP4 and miR-34a, miR-382, and miR-3188; MAPK9 and miR-1275, MAP2K7 and mir-200-5p; MAP3K2 and mir-200-5p, which may be the subject of further research in the context of psoriasis." (PMID 38445655, 2024).
scleroderma (1 paper, 2021). Scleroderma is a rare autoimmune connective tissue disorder characterized by abnormal hardening of the skin and, sometimes, other organs. "We note 38 of the genes found expressed in T cells TADs encompassing the scleroderma associated SNPs were also found to be differentially expressed in Dolcino’s study, including BSG, FCER2, GPA33, MAP2K7, SCAMP2, and TSPAN33." (PMID 33894768, 2021).
scrapie (1 paper, 2014). A fatal disease of the nervous system in sheep and goats, characterized by pruritus, debility, and locomotor incoordination. "Although dual specificity mitogen-activated protein kinase kinase 7 (MKK7), which is also involved in this pathway, clustered distantly, its expression levels were also somewhat lower in scrapie- than in mock-infected mice at 130 dpi." (PMID 25183307, 2014).
tumor (281 papers, 2004 to 2026). "Our present findings also indicate that the level of gene expression correlates with the degree of histological malignancy of the tumor, and our survival analysis confirms that lower MAP2K7 gene expression is associated with longer survival among CRC patients." (PMID 41515982, 2025). "We found that compared to wild-type miR-331-3p high-expressing cells, tumor cells with binding site mutations exhibited higher fluorescence levels, indicating the specific binding of miR-331-3p to MAP2K7 protein in NSCLC cells." (PMID 41323393, 2025). "EEF1AKMT3 mediates the methylation of lysine residue 296 of the MAP2K7 protein, which has been implicated in tumor suppression." (PMID 38036730, 2023). "Given that the JNK pathway can act as both a tumour suppressor and as an oncogene we first assessed whether MAP2K7 loss would increase tumour burden in vivo." (PMID 40826108, 2025). "We uncovered that MAP2K7 loss augments tumour survival in vitro and in vivo." (PMID 40826108, 2025). "Furthermore, the results regarding patient survival suggest that lower expression of MAP2K7 is associated with longer survival, which may confirm its role in tumor progression." (PMID 41515982, 2025). "MAP2K7 gene expression was significantly elevated in tumor specimens with higher histological grades." (PMID 41515982, 2025). "Compared to cells overexpressing MAP2K7 alone, we observed reduced cell proliferation, uplifted apoptosis, and decreased cell migration and invasion in tumor cells co-overexpressing MAP2K7 and miR-331-3p." (PMID 41323393, 2025). "Patients with low MAP2K4, MAP2K7 or MAPK8 expression or high MAPK9 or JUN in their tumours had greater metastatic frequency following tamoxifen treatment." (PMID 40826108, 2025). "In conclusion, the MAP2K7 gene is substantially involved in CRC because it promotes tumor development, metastasis, and chemoresistance." (PMID 38419894, 2024). "Mechanistically, the methylation of MAP2K7 by EEF1AKMT3 was shown to impede tumor activity by promoting the stabilization of TP53188." (PMID 38036730, 2023). "Similar to previous results, inhibiting METTL14 expression could impair the proliferation ability and motility of tumor cells, promoting an increase in cell apoptosis; at the same time, it downregulated the expression of MAP2K7, p-ERK, and p-p38MAPK molecules." (PMID 41323393, 2025). "Although for many a function in B cells is unknown, for others (namely Arhgef1, Gadd45g, Sh2b3, and Map2k7), tumor-suppressive and/or antiproliferative activity was described." (PMID 32407433, 2020). "For example, tumours from patients in cluster 1 (n = 11) had significantly more mutations (8.6 vs 3.5 in all other groups) and a significant enrichment of mutations and amplifications in genes from the ERBB signalling pathway (PLCG2, MAP2K7, ERBB4, and CAMK2B)." (PMID 33862582, 2021). "Data from the Human Protein Atlas revealed differential protein expression of MAP2K4, MAP2K7, MAPK8, and MAPK9 between tumor and normal colon tissues; notably, MAPK8 protein expression did not correspond to the mRNA-level findings." (PMID 41515982, 2025). "At the same time, its overexpression promoted the reduction of tumor cell migration and invasion and inhibited EMT in TNBC cell (Hs578T) by targeting mitogen-activated protein kinase kinase 7 (MAP2K7)." (PMID 33916931, 2021). "Human mitogen-activated protein kinase kinase 7(MKK7, also known as MAP2K7, MIM: 603014) belongs to the MAP kinase kinase family, and is identified as a tumor suppressor gene." (PMID 27028764, 2016). "The high MAP2K7 protein expression observed in CRC tissues may promote JNK phosphorylation and activation, supporting tumor progression, as also indicated by previous studies on MAP2K7-mediated oncogenic signaling." (PMID 41515982, 2025). "In contrast, MAP2K7, CELSR3, and PFKP were overexpressed in tumor tissues." (PMID 36339718, 2022).
tumor (continued). "Furthermore, bioinformatics analysis confirmed that MAP2K7 and MAPK8 appear to promote tumor aggressiveness and metastasis, whereas MAPK9 and MAP2K4 may have a protective or regulatory role in early stages of the disease." (PMID 41515982, 2025). "Other novel tumor suppressor genes identified here include KANSL1, a scaffold protein for histone acetylation complexes, BMPR2, a receptor serine/threonine kinase for bone morphogenetic proteins, MAP2K7, involved in MAP-kinase signaling, and NIPBL, a member of the cohesin complex." (PMID 29056346, 2017). "In the A431 and UT-SCC-7 cell lines, the absence of miR-125b stimulates tumor cell growth, migration, invasion, inflammation and angiogenesis, apparently by targeting MMP7, MMP13 and MAP2K7, as discovered through bioinformatic analyses." (PMID 32674318, 2020). "Referring to the TCGA HNSC tumor dataset, we found a positive correlation between IFN-γ-related genes (IFN-γ, CD8A, and STAT1) and PD-L1 (CD274), but not between EGF-related genes (EGFR, AKT1, and MAP2K7), which seems to support the results of this study." (PMID 35456895, 2022).